EIF4A2 (eukaryotic translation initiation factor 4A2)
Description:
ATP-dependent RNA helicase which is a subunit of the eIF4F complex involved in cap recognition and is required for mRNA binding to ribosome. In the current model of translation initiation, eIF4A unwinds RNA secondary structures in the 5'-UTR of mRNAs which is necessary to allow efficient binding of the small ribosomal subunit, and subsequent scanning for the initiator codon.
Synonyms: eIF-4A-II; eIF4A-II; DDX2B; EIF4F; EIF4A; BM-010; NEDHSS
Tractability: PROTAC: ubiquitination databases record sites on it; its protein half-life has been measured.
Target class: Enzyme; Hydrolase
Gene: Protein-coding gene on chromosome 3 (186,783,205 to 186,789,901, forward strand). Ensembl gene ENSG00000156976.
Subcellular location (Human Protein Atlas): Cytosol
Pathways (Reactome):
Metabolism of proteins: Activation of the mRNA upon binding of the cap-binding complex and eIFs, and subsequent binding to 43S; GTP hydrolysis and joining of the 60S ribosomal subunit; L13a-mediated translational silencing of Ceruloplasmin expression; Ribosomal scanning and start codon recognition; Translation initiation complex formation
Developmental Biology: M-decay: degradation of maternal mRNAs by maternally stored factors; Z-decay: degradation of maternal mRNAs by zygotically expressed factors
Disease: Dengue Virus Genome Translation and Replication
Immune System: ISG15 antiviral mechanism
Metabolism of RNA: Deadenylation of mRNA
Gene Ontology:
Molecular function: ATP hydrolysis activity; protein binding; RNA binding; helicase activity; translation initiation factor activity; ATP binding; nucleic acid binding; RNA helicase activity
Biological process: negative regulation of RNA-dependent RNA polymerase activity; cytoplasmic translational initiation; regulation of translational initiation; translational initiation
Cellular component: perinuclear region of cytoplasm; cytosol; eukaryotic translation initiation factor 4F complex
Genetic constraint (gnomAD): Loss-of-function variants: 9 observed, 52.74 expected, observed/expected ratio (o/e) 0.17, 90% interval 0.1 to 0.3. The synonymous counts are far from expectation, so gnomAD's model fits this gene poorly and the ratio says little. Missense variants: 182 observed, 524.09 expected, observed/expected ratio (o/e) 0.35, 90% interval 0.31 to 0.39. Synonymous variants: 215 observed, 173.38 expected, observed/expected ratio (o/e) 1.24, 90% interval 1.11 to 1.39.
Homologues: Orthologues: chimpanzee EIF4A2 (100% identical), guinea pig EIF4A2 (100% identical), macaque EIF4A2 (100% identical), mouse Eif4a2 (100% identical), rat Eif4a2 (98% identical), tropical clawed frog eif4a2 (97% identical), zebrafish eif4a2 (97% identical). Paralogues in human: EIF4A1 (90% identical), EIF4A3 (68% identical), DDX19B (38% identical), DDX19A (37% identical), DDX39B (36% identical), DDX25 (36% identical), DDX39A (35% identical), DDX6 (34% identical), DDX3X (34% identical), DDX17 (33% identical), DDX21 (33% identical), DDX3Y (33% identical), and 26 more.
Diseases named in the same sentence as EIF4A2 in open-access papers:
EIF4A2 is named in the same sentence as 56 diseases in open-access papers, as found by Europe PMC text mining. Sharing a sentence is not in itself a finding about the gene and the disease. The quoted sentences say what the papers report.
breast carcinoma (12 papers, 2011 to 2025). "We found that heterozygotes of OR8S1 rs11168618 (T/C) and EIF4A2 rs266719 (T/C) were negatively associated with breast cancer risk, whereas the heterozygote of KCNK9 rs2468677 (C/A) had an elevated risk." (PMID 34367982, 2021). "The heterozygous TC genotype of EIF4A2 rs266719 (T/C) decreased breast cancer risk compared with the major CC genotype in model 2 (HR, 0.65; 95% CI, 0.44–0.95)." (PMID 34367982, 2021). "High EIF4A2 expression in non-small cell lung cancer and breast cancer was reported to be associated with better prognosis, which contradicted with our findings here." (PMID 31088567, 2019). "In addition, an even higher association of IER5 and RBM23 and EIF4A2 were found in breast cancer patients (r = 0.75 and p < 0.0001 for RBM23, and r = 0.65 and p < 0.0001 for EIF4A2)." (PMID 26754925, 2016). "Srsf3 KO inhibits expression of Mfsd4a and Eif4a2 in breast cancer but enhances Mfsd4a and Eif4a2 expression in liver cancer." (PMID 40568073, 2025). "We found by RNA-seq that Srsf3 KO promoted the exon 11 inclusion of Eif4a2 splicing and reduced Eif4a2 RNA level due to induction of Eif4a2 RNA degradation in breast cancer." (PMID 40568073, 2025). "The expression of EIF4A2 has also been shown to have a favorable correlation with the prognosis of non-small cell lung cancer and breast cancer in a number of studies." (PMID 37026000, 2023). "As expected, we found EIF4A2 was upregulated in PTX-resistant breast cancer tissues and negatively correlated with miR-5195-3p expression." (PMID 31308851, 2019). "We next measured the EIF4A2 mRNA expression level in PTX-resistant breast cancer tissues and found that it was significantly higher in PTX-resistant breast cancer tissues than in PTX-sensitive samples." (PMID 31308851, 2019). "High EIF4A2 was also reported to be a prognostic factor of breast cancer and non-small cell lung cancer." (PMID 31088567, 2019). "EIF4A2 is involved in the progression of breast cancer and melanoma and in the development of non-small-cell lung cancer, and has been suggested as a potential prognostic marker." (PMID 27835598, 2016). "Luciferase assays using a reporter carrying a putative target site in the 3' untranslated region of ANKRD46 revealed that miR-21 directly targeted ANKRD46. miR-21 and EIF4A2 protein were inversely expressed in breast cancers (rs = -0.283, P = 0.005, Spearman's correlation analysis)." (PMID 21219636, 2011). "Pearson correlation analysis further showed an inverse correlation between the levels of EIF4A2 and miR-5195-3p in PTX-resistant breast cancer tissues (p = 0.0202)." (PMID 31308851, 2019). "Consistently with Erbb2 cancer tissues, knockdown of Srsf3 expression in mouse Erbb2+ NF639 cells and two human breast cancer cell lines ER+ MCF7 and HER2+ SKBR3 cells was also found to promote exon 11 inclusion of Eif4a2 and subsequently to inhibit the production of eIF4A2 protein." (PMID 40568073, 2025). "In breast cancer, apoptosis following paclitaxel treatments is boosted by miR-7-5p, miR-542-3p, miR-621, and miR-5195-3p via directly modulating BCL-2, survivin, F-box protein 11 (FBXO11), and eukaryotic translation initiation factor 4A2 (EIF4A2), respectively." (PMID 33066509, 2020).
non-small cell lung carcinoma (6 papers, 2016 to 2023). A group of at least three distinct histological types of lung cancer, including non-small cell squamous cell carcinoma, adenocarcinoma, and large cell carcinoma. "Conversely, eIF4A2 is present at high levels in resting cells and low levels of eIF4A2 has been associated with poor outcome for patients with breast and non-small-cell lung cancers." (PMID 31795417, 2019). "In addition, EIF4A2 was associated with elevated cell proliferation in rheumatoid arthritis, non-small-cell lung cancer and malignant peripheral nerve sheath tumors." (PMID 31308851, 2019). "Recent articles have suggested that dysregulated expression of EIF4A2 significantly correlates to several types of cancer, including non-small cell lung cancer and malignant peripheral nerve sheath tumors." (PMID 31308851, 2019).
melanoma (5 papers, 2002 to 2023). A malignant, usually aggressive tumor composed of atypical, neoplastic melanocytes. "High EIF4A2 level was prognostic of poor prognosis in liver cancer, head and neck cancer, melanoma and prostate cancer by TCGA data analysis, which was in accordance with our results that EIF4A2 was associated with poor prognosis in CRC." (PMID 31088567, 2019). "Silvestrol targets at EIF4A1 and EIF4A2, silvestrol also have the potential to act as cancer immunotherapies in melanoma." (PMID 31088567, 2019). "This assumption is further promoted by the finding that only eIF-4A1 but none of the other group 4 translation factors (eIF-4E, eIF-4B, eIF-4G, eIF-4A2) was significantly upregulated in melanoma cells as compared to normal melanocytes." (PMID 12085193, 2002). "Interestingly, TCGA patient data analysis also showed that EIF4A2 expression was prognostic of poor prognosis in liver cancer, head and neck cancer, melanoma and prostate cancer." (PMID 31088567, 2019). "The transcripts of 6 significantly changed proteins (VIM, DNM1, SMARCC2, CSDE1, EIF4A2 and ANXA2) have been previously identified as direct RNA targets of CSDE1 in human melanoma cells." (PMID 29129916, 2017).
colorectal cancer (4 papers, 2018 to 2023). A primary or metastatic malignant neoplasm that affects the colon or rectum. "On the other hand, a recent study found that higher EIF4A2 expression in colorectal cancer (CRC) was linked to a worse chance of survival." (PMID 37026000, 2023). "The MSK-IMPACT analysis showed the proportion of EIF4A2 DNA amplification in CRC was only 0.8%, while our study found that EIF4A2 mRNA and protein expression in colorectal cancer was up to approximately 40%." (PMID 31088567, 2019). "Here, we performed a series of cell-biological assays to explore the effects of knocking-down EIF4A2 on experimental metastasis and oxaliplatin resistance in colorectal cancer." (PMID 31088567, 2019). "In addition, either eIF4A2 knockdown or inhibition by silvestrol significantly suppresses colorectal cancer invasion and migration as well as enhances sensitivity to oxaliplatin treatment both in vitro and in vivo." (PMID 34869305, 2021). "Given the prognostic value of EIF4A2 in colorectal cancer, we examined next whether EIF4A2 could serve as a therapeutic target." (PMID 31088567, 2019). "Conclusion: eIF4A2 is required for hypoxic tumour cell survival in colorectal cancer." (PMID 30405205, 2018).
Dystonia (3 papers, 2024 to 2025). An abnormally increased muscular tone that causes fixed abnormal postures. "Of note, the genetic variants of EIF4G1 and EIF3E have been linked to PD, while EIF4A2 has been described in pediatric cases with developmental delay and dystonia-tremor syndrome." (PMID 40194557, 2025). "While a recent association of dystonia with mutation in the EIF4A2 gene highlights the functional intersection between dystonia and the translational initiation process." (PMID 38557486, 2024). "Other dystonia genes with likely pathogenic or pathogenic variants were EIF2AK2 (n = 5 index patients), ANO3 (n = 2), EIF4A2 (n = 1), and TOR1A (n = 1) for genes causing isolated dystonia." (PMID 40533913, 2025). "Of these, the genes VPS16, EIF2AK2, and EIF4A2, which were relatively recently associated with dystonia, were not included in the prescreening process." (PMID 40533913, 2025). "The frequencies of these genetic forms in our dystonia sample were 0.9% (17/1895 index patients) for VPS16, 0.3% (5/1895) for EIF2AK2, and 0.05% (1/1895) for EIF4A2." (PMID 40533913, 2025).
colorectal tumor (2 papers, 2019 to 2021). "Recently, eIF4A2 was indicated to be a regulator of hypoxic translation and colorectal tumor cell survival." (PMID 34440794, 2021). "Immunohistochemistry study of EIF4A2 was carried out in 297 paired colorectal tumor and adjacent normal tissue samples." (PMID 31088567, 2019). "EIF4A2 Expression is significantly higher in colorectal tumors." (PMID 31088567, 2019).
epilepsy (2 papers, 2021 to 2025). A brain disorder characterized by episodes of abnormally increased neuronal discharge resulting in transient episodes of sensory or motor neurological dysfunction, or psychic dysfunction. "EIF4A2-encoding gene mutations cause epilepsy and cerebral anomalies in humans, and transfecting Drosophila with these mutations perturbs decapentaplegic signaling, which regulates eye development." (PMID 40649110, 2025).
esophageal squamous cell carcinoma (2 papers, 2021 to 2023). Esophageal squamous cell carcinoma (ESCC) is a type of esophageal carcinoma (EC) that can affect any part of the esophagus, but is usually located in the upper or middle third. "Recently, high levels of eIF4A2 were associated with poor prognosis in esophageal squamous cell carcinoma." (PMID 37888706, 2023). "In esophageal squamous cell carcinoma, eIF4A2 has been found to be more highly expressed in neoplastic tissues than in normal tissues, and patients with high expression levels of eIF4A2 tend to have a poorer prognosis." (PMID 34869305, 2021). "Furthermore, the univariate and multivariate analyses have suggested that eIF4A2 is an independent prognostic factor in esophageal squamous cell carcinoma." (PMID 34869305, 2021).
gastric cancer (2 papers, 2016 to 2021). A primary or metastatic malignant neoplasm involving the stomach. "Functional analysis of TRIM28, EIF4A2, NAP1L1, PLD3, RPL18A, and TRPM7 suggested that they play direct roles in gastric cancer." (PMID 27835598, 2016).
lung carcinoma (2 papers, 2020 to 2022). "Even though further studies are necessary to shed light on this matter, a role for EIF4A2 in lung cancer and in other cancer types has been previously proposed, indicating that these mutations might have a driver, rather than passenger, role in tumorigenesis." (PMID 32046192, 2020). "To identify if EIF4A1 and EIF4A2 expression were correlated with lung cancer development, we assessed the expression of both genes in normal and LUAD tumor tissue using a TCGA cohort." (PMID 36101357, 2022).
schizophrenia (2 papers, 2016 to 2021). A major psychotic disorder characterized by abnormalities in the perception or expression of reality. "While Silberberg and colleagues found TFRC and RPLP0 as the most stable reference genes in schizophrenia and bipolar disorders, Penna and colleagues found CYC1 and EIF4A2 as the best reference genes in Alzheimer’s disease." (PMID 27754318, 2016).
triple-negative breast carcinoma (2 papers, 2019 to 2021). An invasive breast carcinoma which is negative for expression of estrogen receptor (ER), progesterone receptor (PR), and human epidermal growth factor receptor 2 (HER2). "In triple-negative breast cancer, miR-5195-3p upregulation increases the sensitivity of cancer cells to paclitaxel; the silencing of eIF4A2 mimics this effect, and the restoration of eIF4A2 blocks this effect." (PMID 34869305, 2021). "Functional experiments have further suggested that eIF4A2 knockdown significantly inhibits triple-negative breast cancer cell proliferation and induces apoptosis." (PMID 34869305, 2021).
bladder cancer (1 paper, 2016). "Expression of IER5 and cancer-associated HSF1 target genes (RBM23 and EIF4A2) showed a significant association in bladder cancer (r = 0.64 and p < 0.0001 for RBM23, and r = 0.54 and p < 0.0001 for EIF4A2)." (PMID 26754925, 2016).
diabetes (1 paper, 2024). "Our approach discovered two novel gene variants EIF4A2/ADIPOQ-rs114108468 and TPRG1-rs16864075 on 3q28 for ΔTHR among subjects without diabetes." (PMID 39557295, 2024).
glioblastoma (1 paper, 2019). The most malignant astrocytic tumor (WHO grade IV). "Moreover, to investigate the reliability and the integrity of our NGS transcription data results for each compartment, we evaluated the expression of genes considered as housekeeping candidates in human normal brain tissue, glioblastoma and endothelial cells (RPL13A, RPL4, CYC1, EIF4A2)." (PMID 31231613, 2019).
lymph node metastasis (1 paper, 2019). "Univariate analysis showed that EIF4A2 expression, lymph node metastasis, vascular thrombosis, pathology differentiation, TNM stage, nerve invasion, distant metastasis status were prognostic factors of OS." (PMID 31088567, 2019).
mucinous tumors (1 paper, 2012). "These include: FH, GMPS, PIK3CA, EIF4A2, ZNF384, and SS18L1 (amplifications in serous tumors); TET2, FGFR10P, NF1, ERBB2, and SH3GL1 (deletions in serous tumors) and ERBB2 (amplifications in mucinous tumors)." (PMID 23078675, 2012).
osteosarcoma (1 paper, 2024). A usually aggressive malignant bone-forming mesenchymal neoplasm, predominantly affecting adolescents and young adults. "We showed that human and dog osteosarcoma cells expressed high levels of eIF4A1/2, particularly eIF4A2." (PMID 38947012, 2024).
Parkinson disease (1 paper, 2020). A progressive degenerative disorder of the central nervous system characterized by loss of dopamine producing neurons in the substantia nigra and the presence of Lewy bodies in the substantia nigra and locus coeruleus. "Protein coding genes proximal to these snoRNAs were implicated in several neurologic conditions, including Wernicke‐Korsakoff Syndrome (Tex2/SNORD104), Spinocerebellar Ataxia (Nop56/SNORD57), and Parkinson Disease (EIF4A2/SNORD2)." (PMID 33135344, 2020).
skin cancer (1 paper, 2015). "Finally, genes AI593442 (ACR7 = −1.82 fold, ACR14 = 1.20 fold), Fam126b (ACR7 = −1.48 fold, ACR14= 1.21 fold) and Eif4a2 (ACR7 = −1.46 fold, ACR14= 1.36 fold), are respectively still unknown; unidentified; and play a role in breast, lung and skin cancer." (PMID 26286955, 2015).
type-2 diabetes (1 paper, 2007). "Interestingly, EIF4A2 has also been linked to type-2 diabetes and in rat cells appears to suppress insulin expression." (PMID 17244347, 2007).